NUP93 (nucleoporin 93)
Description:
Plays a role in the nuclear pore complex (NPC) assembly and/or maintenance. May anchor nucleoporins, but not NUP153 and TPR, to the NPC. During renal development, regulates podocyte migration and proliferation through SMAD4 signaling.
Synonyms: KIAA0095; NIC96
Tractability: Antibody: UniProt places it where antibodies can reach, with medium confidence. PROTAC: ubiquitination databases record sites on it; its protein half-life has been measured.
Gene: Protein-coding gene on chromosome 16 (56,730,095 to 56,850,286, forward strand). Ensembl gene ENSG00000102900.
Subcellular location: Nucleus membrane; Nucleus, nuclear pore complex; Nucleus envelope
Pathways (Reactome):
Disease: Defective TPR may confer susceptibility towards thyroid papillary carcinoma (TPC); HCMV Early Events; HCMV Late Events; NEP/NS2 Interacts with the Cellular Export Machinery; NS1 Mediated Effects on Host Pathways; Nuclear import of Rev protein; Rev-mediated nuclear export of HIV RNA; SARS-CoV-2 activates/modulates innate and adaptive immune responses; Transport of Ribonucleoproteins into the Host Nucleus; Viral Messenger RNA Synthesis; Vpr-mediated nuclear import of PICs
Metabolism of RNA: Transport of Mature mRNA Derived from an Intronless Transcript; Transport of Mature mRNA derived from an Intron-Containing Transcript; Transport of the SLBP Dependant Mature mRNA; Transport of the SLBP independent Mature mRNA; snRNP Assembly; tRNA processing in the nucleus
Metabolism of proteins: SUMOylation of DNA damage response and repair proteins; SUMOylation of DNA replication proteins; SUMOylation of RNA binding proteins; SUMOylation of SUMOylation proteins; SUMOylation of chromatin organization proteins; SUMOylation of ubiquitinylation proteins
Metabolism: IP3 and IP4 transport between cytosol and nucleus; IP6 and IP7 transport between cytosol and nucleus; IPs transport between nucleus and cytosol; Regulation of Glucokinase by Glucokinase Regulatory Protein
Cell Cycle: Nuclear Pore Complex (NPC) Disassembly; Postmitotic nuclear pore complex (NPC) reformation
Cellular responses to stimuli: Regulation of HSF1-mediated heat shock response
Immune System: ISG15 antiviral mechanism
Gene Ontology:
Molecular function: protein binding; structural constituent of nuclear pore
Biological process: nuclear envelope organization; nuclear pore complex assembly; positive regulation of SMAD protein signal transduction; nucleocytoplasmic transport; poly(A)+ mRNA export from nucleus; protein import into nucleus
Cellular component: membrane; nuclear envelope; nuclear membrane; nuclear periphery; nuclear pore; cytosol; centrosome
Genetic constraint (gnomAD): Loss-of-function variants: 47 observed, 89.12 expected, observed/expected ratio (o/e) 0.53, 90% interval 0.42 to 0.67. The upper end of that interval is the gene's LOEUF score, 0.67, which puts it in group 2 of 6, group 1 being the genes least tolerant of losing a copy. Missense variants: 849 observed, 987.71 expected, observed/expected ratio (o/e) 0.86, 90% interval 0.81 to 0.91. Synonymous variants: 369 observed, 381.24 expected, observed/expected ratio (o/e) 0.97, 90% interval 0.89 to 1.05.
Gene-disease validity (ClinGen):
ClinGen rates the evidence that NUP93 causes each of these diseases.
nephrotic syndrome, type 12 (autosomal recessive): Definitive.
Homologues: Orthologues: macaque NUP93 (99% identical), rabbit NUP93 (99% identical), dog NUP93 (98% identical), mouse Nup93 (98% identical), rat Nup93 (98% identical), chimpanzee NUP93 (96% identical), guinea pig NUP93 (95% identical), pig NUP93 (95% identical), tropical clawed frog nup93 (85% identical), zebrafish nup93 (84% identical), Drosophila melanogaster Nup93-2 (36% identical), Drosophila melanogaster Nup93-1 (35% identical), and 1 more.
Diseases named in the same sentence as NUP93 in open-access papers:
NUP93 is named in the same sentence as 50 diseases in open-access papers, as found by Europe PMC text mining. Sharing a sentence is not in itself a finding about the gene and the disease. The quoted sentences say what the papers report.
focal segmental glomerulosclerosis (6 papers, 2019 to 2024). A renal disorder characterized by sclerotic lesions in the glomeruli. "For example, focal segmental glomerulosclerosis (FSGS), which is caused by deficient podocytes, is now believed to be associated with mutations in Nup93 and Nup205." (PMID 39768219, 2024). "Six novel homozygous and compound heterozygous NUP93 variants were detected in 3 sporadic and 2 familial paediatric onset SRNS characterised histologically by focal segmental glomerulosclerosis (FSGS) and progressing to kidney failure by 12 months from clinical diagnosis." (PMID 35211795, 2022). "Pathological mutations in NUP93 have been implicated in early-onset, severe kidney diseases, such as SRNS and focal segmental glomerulosclerosis (FSGS), with studies revealing its essential role in kidney cell function." (PMID 39080077, 2024). "Knockdown of NUP93 leads to inhibition of podocytes proliferation by impairing SMAD signaling resulting in focal segmental glomerulosclerosis (FSGS)." (PMID 31315584, 2019).
nephrotic syndrome (6 papers, 2019 to 2025). A collection of symptoms that include severe edema, proteinuria, and hypoalbuminemia; it is indicative of renal dysfunction. "Compound heterozygote or homozygote mutations in the NUP93 gene have been associated with FSGS-related nephrotic syndrome." (PMID 41209161, 2025). "Diseases associated with NUP93 include nephrotic syndrome and genetic steroid-resistant nephrotic syndrome." (PMID 35211510, 2022). "Here we describe a case of recessive, syndromic, steroid-resistant nephrotic syndrome caused by NUP93 mutation." (PMID 31315584, 2019). "NUP93 mutations can lead to steroid-resistant nephrotic syndrome." (PMID 35211510, 2022). "NUP93 is a gene previously reported to cause isolated steroid-resistant nephrotic syndrome." (PMID 31315584, 2019).
breast carcinoma (5 papers, 2011 to 2023). "To elucidate the mechanisms underlying Nup93 involvement in triple-negative, claudin-low breast cancer progression, we used microfluidic assays, RNAseq, and profiling of Nup93–chromatin interactions." (PMID 31959624, 2020). "NUP93 regulated the growth of breast cancer cells by modulating actin cytoskeleton remodeling and cell proliferation." (PMID 35211510, 2022). "Our approach identified Nup93 as contributor of triple-negative, claudin-low breast cancer cell invasion and paves the way to study the role of nuclear envelope proteins during breast cancer tumorigenesis." (PMID 31959624, 2020). "Clinical data also suggest that higher Nup93 expression correlates with reduced breast cancer patient survival." (PMID 31959624, 2020). "Clinical data showed that NUP93 expression is higher in basal, Her2+, and triple-negative, claudin-low breast cancers than in luminal breast cancer and normal breast tissue." (PMID 31959624, 2020). "By applying to the exome and RNA sequencing data of 78 normal-paired breast cancer samples we collected from 1998 to 2008, our approach identifies five driver mutations in ADPGK, NUP93, PCGF6, PKP2 and SLC22A5 genes." (PMID 27625789, 2016). "NUP93 was identified as one of the top 10 breast cancer drivers, based on the impacts on global gene expression, and the amplification of NUP93-containing chromosome was reported in breast cancer." (PMID 27625789, 2016). "Known breast cancer susceptibility genes like TPX2, AURKA, TK1 and BIRC5 are among the top 7 global drivers (the other 3 top drivers are GINS2, COX4NB and NUP93)." (PMID 21806811, 2011). "However, our knowledge of Nup93 function in breast cancer besides its role as structural component of the nuclear pore complex is not understood." (PMID 31959624, 2020). "In particular, Nup93 might represent an attractive new therapeutic target because Nup93 mutations can increase both cell migration and the expression of epithelial to mesenchymal transition (EMT) markers in breast cancer." (PMID 31959624, 2020). "We discovered a novel and unexpected role of Nup93 in triple-negative, claudin-low breast cancer." (PMID 31959624, 2020). "To confirm this hypothesis, we generated mammary tumors within immunocompromised mice (N = 7 per group) by orthotopically transplanting doxycycline-inducible eGFP NUP93 KD and dsRed control cells at a 1:1 ratio." (PMID 31959624, 2020). "The effect of NUP93 silencing on AC remodeling appears not to be limited to this breast cancer subtype as we observed changes, although more modest, in luminal A MCF-7, HER2+ MDA-361, and triple-negative BT-20 cell lines as well as in non–small cell lung cancer cells H1299." (PMID 31959624, 2020).
viral infections (4 papers, 2018 to 2025). "This suggests a close association between NUP93 and viral infections." (PMID 40407330, 2025). "Nuclear pore complex proteins are also targets of various viral infections and NUP93 has specifically been shown to be an important player in viral mRNA nuclear-cytoplasmic export." (PMID 35110370, 2022). "Additionally, in DF-1 cells infected with H5N6-JX, PB1 was immunoprecipitated by endogenous NUP93, suggesting a critical role for NUP93 during viral infection." (PMID 40407330, 2025). "In addition, Western blot experiments confirmed that the expression of Nup93 was significantly downregulated in lycorine treatment but induced after viral infection." (PMID 31592345, 2019). "Therefore, NUP93 likely plays important roles in actual virus infection of humans." (PMID 30087672, 2018). "GO and KEGG pathway analyses revealed that Nup93, as an important NPC component that directs nucleocytoplasmic transport, was induced by virus infection but sharply decreased by lycorine treatment." (PMID 31592345, 2019).
colorectal cancer (3 papers, 2016 to 2023). A primary or metastatic malignant neoplasm that affects the colon or rectum. "Here, we examined the association of Nup93 with the HOXA gene cluster and its consequences on HOXA gene expression in diploid colorectal cancer cells (DLD1)." (PMID 27980680, 2016). "We show that Nup93 associates with and represses HOXA gene expression in a manner dependent on its interacting partners—Nup188 and Nup205, in diploid colorectal cancer cells (DLD1)." (PMID 27980680, 2016). "In particular, since NUP93 chromatin-binding has been reported in Drosophila S2 cells and in the colorectal cancer cell line DLD-145,47, it will be interesting in the future to clarify if NUP93 can bind to chromatin in keratinocytes and if NUP93 binding reduces in differentiation." (PMID 37853046, 2023). "Nup93 was recently shown to regulate gene expression in colorectal cancer cells." (PMID 31959624, 2020). "The focus of our study was to examine the consequences of depleting Nup93 and its interactors on HOXA gene expression in diploid colorectal cancer cells (DLD1)." (PMID 27980680, 2016).
cervical cancer (2 papers, 2022 to 2025). A primary or metastatic malignant neoplasm involving the cervix. "NUP93 is confirmed to be overexpressed in hepatocellular carcinoma, esophageal cancer, cervical cancer, and bladder cancer." (PMID 40861463, 2025). "The knockdown of NUP93 could inhibit the proliferation, invasion, and migration of cervical cancer cells." (PMID 35211510, 2022).
ciliopathies (2 papers, 2023 to 2025). "However, the key cilia-related parameters, such as beating frequency and ultrastructure, in individuals bearing NUP93 mutations have not been investigated, despite nephrotic syndrome commonly being associated with ciliopathies." (PMID 37908226, 2023). "Although these outcomes strongly support the functional involvement of NUP93 in cilia, no direct evidence yet substantiates the connection between NUP93 variations and human ciliopathies." (PMID 37908226, 2023).
dilated cardiomyopathy (2 papers, 2024 to 2025). Cardiomyopathy which is characterized by dilation and contractile dysfunction of the left and right ventricles. "The knockdown of nup93 promotes apoptosis in cardiomyocytes and its aberrant upregulated or downregulated expression is associated with dilated cardiomyopathy and coronary heart disease, respectively, in mice." (PMID 38777147, 2024).
influenza (2 papers, 2025). An acute viral infection of the respiratory tract, occurring in isolated cases, in epidemics, or in pandemics; it is caused by serologically different strains of viruses (influenzaviruses) designated A, B, and C, has a 3-day incubation period, and usually lasts for 3 to 10 days. "However, the mechanism underlying the downregulation of NUP93 expression during influenza infection remains unclear and requires further investigation." (PMID 40407330, 2025). "In conclusion, our study identifies lycorine as a promising broad-spectrum anti-influenza agent with a unique mechanism of action involving the host nuclear pore protein Nup93." (PMID 40508167, 2025).
pancreatic cancer (2 papers, 2020 to 2026). "The APA status of NUP93 in glioma, in addition to pancreatic cancer, is also tumor-specific." (PMID 32626751, 2020). "Therefore, with a unique APA status in pancreatic cancer and glioma, the predicted NUP93 may be an effective indicator for the identification of different tumor types." (PMID 32626751, 2020). "In our study, NUP93 was APA modified in gastrointestinal diseases, including pancreatic cancer; thus, the APA status of NUP93 may be a potential indicator for the identification of pancreatic cancer." (PMID 32626751, 2020).
prostate carcinoma (2 papers, 2018 to 2024). A carcinoma that arises from epithelial cells of the prostate gland. "Some of the identified mRNA isoforms are in genes already implicated in prostate cancer (includingLIG4,FDFT1 andRELAXIN), or in genes important in other cancers (e.g.NUP93 andMAT2A)." (PMID 30271587, 2018).
triple-negative breast carcinoma (2 papers, 2020 to 2022). An invasive breast carcinoma which is negative for expression of estrogen receptor (ER), progesterone receptor (PR), and human epidermal growth factor receptor 2 (HER2). "A high level of NUP93 was significantly associated with unfavorable survival in triple-negative breast cancer." (PMID 35211510, 2022). "This study highlights the role of Nup93-chromatin interactions in driving triple-negative breast cancer propagation through modulation of the actin cytoskeleton, cell migration and proliferation." (PMID 31959624, 2020). "Nucleoporin 93 (Nup93) expression inversely correlates with the survival of triple-negative breast cancer patients." (PMID 31959624, 2020).
breast tumor (1 paper, 2020). "In this scenario, our findings extend previous studies showing chromatin interactions of Nup93 and reveal a critical role of this protein in BCC migration and breast tumor growth, hence paving the way for the study of other nucleoporins and NE proteins during tumor initiation, EMT, and metastases." (PMID 31959624, 2020). "Because NUP93 silenced cells did not significantly contribute to breast tumor formation and propagation in vivo, we then hypothesized that the level of Nup93 and other proteins directly regulated by Nup93 (e.g., LIMCH1) could be correlated with the progression of the disease in patients." (PMID 31959624, 2020).
clear cell renal cell carcinoma (1 paper, 2024). "High expression of Nup93 in clear cell renal cell carcinoma tissue is associated with reduced overall survival of the patients." (PMID 38777147, 2024).
congenital heart disease (1 paper, 2024). A heart disease that is present at birth. "Previous studies have linked NUP93, NUP107 and NUP160 to cancer, congenital heart disease, neurological diseases and gonadal dysgenesis." (PMID 38650033, 2024).
endothelial dysfunction (1 paper, 2024). In vascular diseases, endothelial dysfunction is a systemic pathological state of the endothelium (the inner lining of blood vessels) and can be broadly defined as an imbalance between vasodilating and vasoconstricting substances produced by (or acting on) the endothelium. "To definitively link enhanced Yap activity as the primary mechanism of endothelial dysfunction in Nup93‐deficient human ECs, we introduced verteporfin (VP), a potent pharmacological inhibitor of Yap." (PMID 38348753, 2024).
HIV-1 infection (1 paper, 2018). The type species of lentivirus and the etiologic agent of acquired immunodeficiency syndrome (AIDS). "Perturbation of the NUP155 and the Nup93 complex also impacted the effect of CA mutations and CypA on HIV-1 infection." (PMID 30084827, 2018). "Overall, manipulations of NUP155 and other Nup93 subcomplex components recapitulated, abolished, or otherwise modified several of the key cell-type- and CA-dependent differences in the effects of CypA and MX2 on HIV-1 infection." (PMID 30084827, 2018). "Moreover, some Nup depletions (SEH1, NUP85, NUP160, SEC13, NUP98, NUP107, ELYS/ACHTF1, NUP93, NUP205, NUP88, and NUP214) that reduced both HIV-1 infection and MX2 activity in dividing HeLa cells, affected MX2 activity but not HIV-1 infection in non-dividing HeLa cells." (PMID 30084827, 2018).
metastatic cancer (1 paper, 2023). A carcinoma which has spread from the original site of growth to another anatomic site. "These different findings indicate that NUP93’s action in gene regulation is highly context-dependent, especially between the normal non-transformed cells and metastatic cancer cells." (PMID 37853046, 2023).
neuroblastoma (1 paper, 2026). Neuroblastoma (NB) is the most common solid, extracranial childhood tumor. "Instead, higher levels of NUP62, NUP93, and NUP98 were correlated with mortality, high-risk, advanced stages of International Neuroblastoma Staging System (INSS), or disease progression in 498 NB patients (GSE62564), and associated with worse survival outcome." (PMID 41510169, 2026).
small cell lung carcinoma (1 paper, 2020). Small cell lung cancer (SCLC) is a highly aggressive malignant neoplasm, accounting for 10-15% of lung cancer cases, characterized byrapid growth, and early metastasis. "Similarly, we previously demonstrated that NUP93 KD induced less pronounced AC modifications in non–small cell lung cancer cells, which showed limited formation of stress fibers and focal adhesions compared with triple-negative, claudin-low BCCs." (PMID 31959624, 2020).
systemic hypertension (1 paper, 2025). "As such, our findings insinuate endothelial Nup93 loss, and consequent eNOS disruption, as a trigger for systemic hypertension and atherosclerotic disease progression, a topic for future reports." (PMID 40777343, 2025).
varicocele (1 paper, 2021). A condition characterized by the dilated tortuous veins of the spermatic cord with a marked left-sided predominance. "Considering the role of NUP153 in DNA repair response and its binding with other NUPs as NPC components, we can speculate that NUP93 might be involved in this type of cellular regulation, explaining why our in silico analysis predicted downregulation of NUP93 in varicocele patients." (PMID 34975746, 2021). "In particular, the analysis showed 2 (FASN, MPO) and 3 (ACO2, NUP93, and PSMD14) proteins, which were significantly over- and under-expressed, respectively (P <0.03) in varicocele samples and reported to be involved in DNA repair function." (PMID 34975746, 2021). "In silico analysis identified two additional proteins (NUP93 and MPO) that were predicted to be significantly altered in varicocele sperm." (PMID 34975746, 2021).